VMA22 (vacuolar ATPase assembly factor VMA22)
Description:
Accessory component of the proton-transporting vacuolar (V)- ATPase protein pump involved in intracellular iron homeostasis. In aerobic conditions, required for intracellular iron homeostasis, thus triggering the activity of Fe(2+) prolyl hydroxylase (PHD) enzymes, and leading to HIF1A hydroxylation and subsequent proteasomal degradation. Necessary for endolysosomal acidification and lysosomal degradation. May be involved in Golgi homeostasis.
Synonyms: CCDC115; MGC12981; FLJ30131; ccp1; CDG2O
Tractability: Antibody: the Human Protein Atlas places it where antibodies can reach. PROTAC: ubiquitination databases record sites on it.
Gene: Protein-coding gene on chromosome 2 (130,337,922 to 130,342,699, reverse strand). Ensembl gene ENSG00000136710.
Subcellular location: Endosome; Lysosome; Endoplasmic reticulum-Golgi intermediate compartment; Cytoplasmic vesicle, COPI-coated vesicle; Endoplasmic reticulum
Subcellular location (Human Protein Atlas): Plasma membrane; Vesicles
Pathways (Reactome):
Signal Transduction: RHOA GTPase cycle
Gene Ontology:
Molecular function: protein binding
Biological process: cellular response to increased oxygen levels; intracellular iron ion homeostasis; lysosomal lumen acidification; lysosomal protein catabolic process; vacuolar proton-transporting V-type ATPase complex assembly
Cellular component: COPI-coated vesicle; endoplasmic reticulum; endoplasmic reticulum-Golgi intermediate compartment; membrane; plasma membrane; vacuolar proton-transporting V-type ATPase complex; endosome; lysosome
Genetic constraint (gnomAD): Loss-of-function variants: 21 observed, 25.25 expected, observed/expected ratio (o/e) 0.83, 90% interval 0.59 to 1.2. The upper end of that interval is the gene's LOEUF score, 1.2, which puts it in group 5 of 6, group 1 being the genes least tolerant of losing a copy. Missense variants: 253 observed, 249.32 expected, observed/expected ratio (o/e) 1.01, 90% interval 0.92 to 1.13. Synonymous variants: 110 observed, 102.13 expected, observed/expected ratio (o/e) 1.08, 90% interval 0.92 to 1.26.
Homologues: Orthologues: macaque CCDC115 (94% identical), pig VMA22 (85% identical), chimpanzee CCDC115 (84% identical), dog CCDC115 (83% identical), rabbit VMA22 (82% identical), guinea pig VMA22 (79% identical), mouse Ccdc115 (79% identical), rat Ccdc115 (79% identical), tropical clawed frog ccdc115 (46% identical), zebrafish ccdc115 (38% identical).
Diseases named in the same sentence as VMA22 in open-access papers:
VMA22 is named in the same sentence as 23 diseases in open-access papers, as found by Europe PMC text mining. Sharing a sentence is not in itself a finding about the gene and the disease.
VMA22 shares sentences with these, for which no sentence is quoted: liver disease (3 papers); tumor (3); Immunodeficiency (2); infection (2); adenocarcinoma (1); cancer (1); cholestasis (1); copper metabolism disorder (1); cutis laxa (1); hair loss (1); Hepatic steatosis (1); hepatoma (1); Hypercholesterolemia (1); hyperlipidemia (1); Hypoglycemia (1); hypothyroidism (1); pericarditis (1); prostate adenocarcinoma (1); prostate carcinoma (1); prostate tumor (1); sensorineural deafness (1); steatosis (1); viral infection (1).